OR1B1 (olfactory receptor family 1 subfamily B member 1)
Description:
Odorant receptor.
Synonyms: OR9-B; OR9-26
Tractability: Antibody: UniProt places it where antibodies can reach, with medium confidence; UniProt predicts a signal peptide or a membrane-spanning region; its Gene Ontology location is reachable by antibodies, with medium confidence.
Gene: Protein-coding gene on chromosome 9 (122,628,125 to 122,657,627, reverse strand). Ensembl gene ENSG00000280094.
Subcellular location: Cell membrane
Pathways (Reactome):
Sensory Perception: Expression and translocation of olfactory receptors
Gene Ontology:
Molecular function: olfactory receptor activity; G protein-coupled receptor activity
Biological process: signal transduction; detection of chemical stimulus involved in sensory perception of smell; G protein-coupled receptor signaling pathway
Cellular component: plasma membrane; membrane
Genetic constraint (gnomAD): Loss-of-function variants: 1 observed, 0.79 expected, observed/expected ratio (o/e) 1.27, 90% interval 0.29 to 1.91. That is too few expected variants to judge how well the gene tolerates losing a copy. Missense variants: 408 observed, 414.28 expected, observed/expected ratio (o/e) 0.98, 90% interval 0.91 to 1.07. Synonymous variants: 165 observed, 161.4 expected, observed/expected ratio (o/e) 1.02, 90% interval 0.9 to 1.16.
Homologues: Orthologues: macaque OR1B1 (91% identical), mouse Or1b1 (87% identical), rat Or1b1 (85% identical), rabbit OR1B1 (82% identical), pig OR1B1 (81% identical), guinea pig OR1B1 (78% identical). Paralogues in human: OR1K1 (46% identical), OR1F1 (46% identical), OR1E1 (45% identical), OR1E2 (44% identical), OR1J4 (44% identical), OR1J1 (44% identical), OR1L6 (44% identical), OR1L3 (44% identical), OR1P1 (43% identical), OR1L4 (43% identical), OR7C1 (43% identical), OR1J2 (43% identical), and 116 more.
Diseases named in the same sentence as OR1B1 in open-access papers:
OR1B1 is named in the same sentence as 2 diseases in open-access papers, as found by Europe PMC text mining. Sharing a sentence is not in itself a finding about the gene and the disease. The quoted sentences say what the papers report.
adenoma (2 papers, 2021 to 2022). A neoplasm arising from the epithelium. "New mutations were found in OR1B1 (GPCR signaling pathway) in adenoma evolution, and LAMA1 (PI3K-Akt signaling pathway) and ADCY3 (FGFR signaling pathway) in CRC evolution." (PMID 35785171, 2022). "These new driver mutations in OR1B1 (GPCR signaling), LAMA1 (PI3K-Akt signal in CRC evolution), and ADCY3 (FGFR signaling) of adenoma evolution and cancer evolution, confirming that both colorectal adenomas and CRC were of monoclonal origin." (PMID 35785171, 2022). "New driver mutations were identified that developed during the evolution of both adenoma and cancer: on one hand OR1B1 (GPCR signaling pathway) was related to adenoma evolution; on the other hand, LAMA1 (PI3K-Akt signaling pathway) and ADCY3 (FGFR signaling pathway) had a role in CRC evolution." (PMID 34833475, 2021).
OR1B1 also shares sentences with these, for which no sentence is quoted: cancer (1 paper).